TXNIP (thioredoxin interacting protein)
Diseases named in the same sentence as TXNIP in open-access papers (continued):
Sharing a sentence is not in itself a finding about the gene and the disease.
diabetic macular edema (1 paper, 2019). "TXNIP is a mediator of mitochondrial fragmentation and mitophagic flux to lysosomes in RPE under diabetic conditions, which could be related to events that occur in early DR and diabetic macular edema." (PMID 31023645, 2019).
esophageal adenocarcinoma (1 paper, 2020). A malignant tumor with glandular differentiation arising predominantly from Barrett mucosa in the lower third of the esophagus. "Consistent with the findings that overexpression of TXNIP promotes DNA damage in esophageal adenocarcinoma, senescence in vascular endothelial cells, we demonstrated that TXNIP, may function downstream of PRMT5 to regulate DNA damage signaling and p21-mediated cellular senescence in U2 OS cells." (PMID 32023548, 2020).
esophageal squamous cell carcinoma (1 paper, 2025). Esophageal squamous cell carcinoma (ESCC) is a type of esophageal carcinoma (EC) that can affect any part of the esophagus, but is usually located in the upper or middle third. "For example, in esophageal squamous cell carcinoma, piperlongumine inhibited tumorigenesis by triggering NRF2/ROS/TXNIP/NLRP3-dependent pyroptosis." (PMID 40125551, 2025).
Ewing sarcoma (1 paper, 2024). A small round cell tumor that lacks morphologic, immunohistochemical, and electron microscopic evidence of neuroectodermal differentiation. "Moreover, from a mechanistic standpoint, SOX6, a transcriptional target of the EWS-FLI1 oncoprotein, was shown to increase ROS and oxidative stress in Ewing sarcoma cells via upregulation of thioredoxin interacting protein (TXNIP), an inhibitor of thioredoxin and inducer of ROS." (PMID 38933441, 2024).
fibrosarcoma (1 paper, 2018). A malignant mesenchymal fibroblastic neoplasm affecting the soft tissue and bone. "To explore the link between the UPR and circadian oscillation we characterized TXNIP and DDIT3 in both SAHA/JQ1-treated UPS and fibrosarcoma cells." (PMID 30382078, 2018).
Follicular carcinomas of the thyroid gland (1 paper, 2020). "Follicular carcinomas of the thyroid gland have a less favorable prognosis and display a considerably lower percentage of TXNIP-positive tumors (19.2%)." (PMID 33081035, 2020).
Granuloma (1 paper, 2022). A compact, organized collection of mature mononuclear phagocytes, which may be but is not necessarily accompanied by accessory features such as necrosis. "The most abundant subcluster (8.3% of granuloma cells, q = 0.074, Dirichlet p = 0.00049) exhibited elevated expression of markers of naive and memory T cells (TCF7, CCR7, IL7R, and TXNIP) and activation or memory state (CD69 and ITGB1)." (PMID 35483355, 2022).
HCMV infection (1 paper, 2018). "Thioredoxin-interacting protein (TXNIP) was extremely rapidly turned over during mock infection, making it difficult to assess a difference between mock and HCMV infection even during the 6-hr pulse." (PMID 30122656, 2018).
hearing loss (1 paper, 2022). "Taken together, our results suggest that NLRP3 inflammasome activation may mediate cisplatin-induced MC pyroptosis in cochlear stria vascularis, and TXNIP is a possible upstream regulator, which may be a promising therapeutic target for alleviating cisplatin-induced hearing loss." (PMID 35529876, 2022).
hematoma (1 paper, 2025). A hematoma is a collection of blood from a vascular structure into an extravascular space. "In a collagenase-induced ICH mouse model, verapamil administration has demonstrated efficacy in reducing TXNIP and NLRP3 expression around the hematoma region, inhibiting NF-κB activation, facilitating hematoma clearance, and improving both neuroinflammation and blood-brain barrier dysfunction." (PMID 40083546, 2025).
hemorrhagic cystitis (1 paper, 2021). Inflammation of the bladder resulting in bloody urine. "Therefore, this study aims to verify the therapeutic effect of LUT on acute hemorrhagic cystitis in rats and to further determine whether the NF-κB signal pathway and the TXNIP/NLRP3 axis are the therapeutic targets of LUT against bladder injury." (PMID 34804174, 2021). "In summary, we found that LUT can inhibit oxidative stress, inflammation, and apoptosis through TXNIP/NLRP3 and NF-κB, which then produces protection against CYP-induced hemorrhagic cystitis and effectively improves bladder voiding dysfunction." (PMID 34804174, 2021). "Therefore, TXNIP/NLRP3 and NF-κB may be potentially effective targets for hemorrhagic cystitis." (PMID 34804174, 2021).
hyperandrogenism (1 paper, 2026). Excessive secretion of androgens from the adrenal glands or gonads. "Our data suggest that DNMT activation, by suppressing proteasome activity, contributes to increases in TXNIP expression, resulting in ovarian fibrosis and GC dysfunction in PCOS-like ovaries after exposure to hyperandrogenism." (PMID 41934343, 2026).
hyperuricemia (1 paper, 2017). An abnormally high level of uric acid. "Furthermore, ROS generation under fructose-induced hyperuricemia is the crucial factor for podocyte injury by activating p38 MAPK/thioredoxin-interacting protein (TXNIP)/NLRP3 inflammasome pathway." (PMID 28353649, 2017).
influenza (1 paper, 2022). An acute viral infection of the respiratory tract, occurring in isolated cases, in epidemics, or in pandemics; it is caused by serologically different strains of viruses (influenzaviruses) designated A, B, and C, has a 3-day incubation period, and usually lasts for 3 to 10 days. "In conclusion, the newly identified Lnc‐PINK1‐2:5 isoform is an anti‐influenza lncRNA acting through the upregulation of TXNIP gene expression." (PMID 35201667, 2022). "In conclusion, Lnc‐PINK1‐2:5 is an anti‐influenza lncRNA acting through the upregulation of TXNIP." (PMID 35201667, 2022).
intracerebral hemorrhage (1 paper, 2025). A cerebrovascular disorder characterized by bleeding into one or both cerebral hemispheres including the basal ganglia and the cerebral cortex. "Interestingly, a recent investigation demonstrated that miR-152 conferred protection against intracerebral hemorrhage-mediated neuroinflammation and brain injury by inhibiting thioredoxin-interacting protein-induced inflammasome activation in both in vivo and in vitro models." (PMID 39879739, 2025).
invasive ductal carcinomas (1 paper, 2020). "Interestingly, in invasive ductal carcinomas, only 13.6% of tumors displayed TXNIP protein expression but retained a diverse expression pattern ranging from weak to high." (PMID 33081035, 2020).
kidney degeneration (1 paper, 2018). "To identify the function of TXNIP in kidney degeneration, we analyzed kidney samples from WT and KO mice at 2, 12, and 20 months of age using hematoxylin and eosin (H&E) staining, SA‐β‐gal staining, or western blotting." (PMID 30168649, 2018).
kidney stone (1 paper, 2024). "However, little is known about TXNIP and kidney stone formation." (PMID 39768161, 2024). "Endoplasmic reticulum stress (ERS) can activate pyroptosis through CHOP and TXNIP; however, the correlation between this process and the formation of kidney stones has not been reported." (PMID 39768161, 2024). "Only studies show that TXNIP, NLRP3, and other genes are upregulated in the in vivo model of kidney stone mice, but they do not link ERS with pyroptosis." (PMID 39768161, 2024).
latent infection (1 paper, 2020). "In regards to gammaherpesviruses, TXNIP expression has been found to be downregulated by EBV lytic infection in B cells, and induced by transgenic expression of LMP2A in mice, while in the case of KSHV, latent infection of endothelial cells results in the induction of TXNIP expression." (PMID 32017809, 2020).
limb ischemia (1 paper, 2017). A ischemia that involves the limb. "Nevertheless, deleting TXNIP abolished HFD-mediated macrophage infiltration after limb ischemia." (PMID 28661427, 2017). "Similarly, silencing TXNIP in diabetic mice restored blood flow recovery and capillary density following hind-limb ischemia." (PMID 28661427, 2017).
liver dysfunction (1 paper, 2024). "Here, through transcriptome analysis we found that transcriptional activation of TXNIP was the main cause of ensartinib-induced liver dysfunction." (PMID 38789868, 2024).
malnutrition (1 paper, 2023). Inadequate nutrition resulting from poor diet, malabsorption, or abnormal nutrient distribution. "The malnutrition–inflammation status of hemodialysis patients did not significantly affect the stimulation of the TXNIP-eNOS-STAT3 endothelial inflammatory response." (PMID 37237975, 2023).
mental disorder (1 paper, 2022). A disease that has its basis in the disruption of mental process. "We indicated a bidirectional function of TXNIP in the brain, whose high expression in the early stage is protective for development but might be harmful in a later period, associated with mental disorders." (PMID 36291328, 2022).
metabolism (1 paper, 2017). "Low blood TXNIP DNA methylation has been associated with elevated glucose levels and risk of T2DM, and increased skeletal muscle TXNIP gene expression was reported in subjects with impaired glucose metabolism or T2DM." (PMID 29077742, 2017).
metastatic cancers (1 paper, 2018). A carcinoma which has spread from the original site of growth to another anatomic site. "Thus, we conclude that high levels of TXNIP in tumoral tissues might be common among invasive and metastatic cancers." (PMID 30627326, 2018).
metastatic prostate carcinoma (1 paper, 2022). A carcinoma that arises from the prostate gland and has spread to other anatomic sites. "Consistent with a tumor suppressor role, we have previously shown that endogenous TXNIP expression is reduced in the M12 metastatic prostate cancer cell line relative to its benign counterpart, and that ectopic TXNIP overexpression in metastatic prostate cancer leads to cell death." (PMID 36291127, 2022).
myeloproliferative diseases (1 paper, 2023). "Supporting this idea, the expression of TXNIP was positively associated with Miz-1 and negatively associated with c-Myc in the samples from patients with myeloproliferative diseases." (PMID 37095099, 2023). "Combination of drug activating TXNIP with imatinib effectively suppresses the development of CML-like myeloproliferative disease in mice, which provides a rationale for treating patients with CML with minimal residual disease." (PMID 37095099, 2023). "In particular, combination of TXNIP induction with imatinib effectively suppresses the development of CML-like myeloproliferative disease in mice, which provides a rationale for treating patients with CML with minimal residual disease." (PMID 37095099, 2023).
Myocardial fibrosis (1 paper, 2025). "It promotes stimulator of interferon genes (STING) translocation to the Golgi apparatus, subsequently activating IRF3, NF-κB, and thioredoxin-interacting protein (TXNIP), culminating in inflammation, apoptosis, and myocardial fibrosis." (PMID 41008547, 2025).
myopia (1 paper, 2024). "In conclusion, our study provided a novel perspective into the miR-204-5p function in myopia and highlighted the possible involvement of the miR-204-5p-TXNIP axis in the modulation of retinal cell behavior and oxidative stress." (PMID 38684840, 2024). "Our findings revealed the possible contribution of the miR-204-5p/TXNIP axis in myopia development by regulating oxidative stress, which may provide new targets to combat this prevalent and debilitating condition." (PMID 38684840, 2024). "Finally, our outcomes revealed that miR-204-5p downregulation may increase TXNIP expression and contribute to myopia development via enhanced oxidant stress." (PMID 38684840, 2024). "It is hypothesized that miR-204-5p downregulation promotes TXNIP expression and may contribute to myopia development by inducing cellular oxidative stress and disrupting retinal cell homeostasis and function while down-regulating anti-oxidative genes (e.g., NRF2) expression." (PMID 38684840, 2024). "Additionally, our study only focused on the regulation of miR-204-5p through TXNIP, and further animal experiments s are warranted to investigate the crosstalk between miR-204-5p and other regulatory molecules or signaling pathways involved in myopia development." (PMID 38684840, 2024).
neuropathic pain (1 paper, 2018). Chronic pain caused by damage to nerve fibers. "Therefore, the present study aimed to determine the functional and regulatory role of miR-23a in pain processing in the CNS and its interplay with CXCR4 and TXNIP at spinal level, which may provide potential therapeutic targets for peripheral injury-induced neuropathic pain." (PMID 29386025, 2018). "Based on the fact that miR-23a/CXCR4 regulates neuropathic pain by directly targeting TXNIP and TXNIP regulates the expression of NLRP3 inflammasome in neuropathic pain, we supposed to investigate whether miR-23a or CXCR4 could regulate NLRP3 inflammasome via TXNIP." (PMID 29386025, 2018).
osteonecrosis (1 paper, 2025). A none disease characterized by death of bone tissue due to a lack of blood supply. "TXNIP, which plays a role in reacting to oxidative stress, was discovered as a potential indicator for glucocorticoid-induced osteonecrosis of the femoral head, connecting ferroptosis to the development of this bone disorder." (PMID 40997129, 2025).
pancreatic adenocarcinoma (1 paper, 2022).
pancreatic disease (1 paper, 2022). "Several key factors support the improvement of pancreatic disease by Uro A. At first, Uro A inhibited ER stress and the TXNIP/NLRP3/IL-1β inflammation signal in β cells by modulating autophagy." (PMID 35745279, 2022).
periodontal diseases (1 paper, 2022). "The ROS/TXNIP/NLRP3 inflammasome signaling pathway may play an important role in the pathogenesis of periodontal disease." (PMID 35083332, 2022). "OSAHS may affect the incidence of periodontal diseases through the ROS/TXNIP/NLRP3 inflammasome signaling pathway." (PMID 35083332, 2022).
peripheral nerve injury (1 paper, 2020). Injury to a peripheral nerve. "Nevertheless, our results from microarray analysis further verified that miR-183 could affect the neuropathic pain by regulating the thioredoxin interacting protein (TXNIP)/NLR family pyrin domain-containing 3 (NLRP3) inflammasome axis in peripheral nerve injury." (PMID 32723328, 2020).
premature ovarian failure (1 paper, 2022). "Furthermore, the characteristics of premature ovarian failure were more significant in Nrf2 knockout mice than in wild-type mice, especially the expression of NLRP3 and TXNIP." (PMID 35153783, 2022).
prostate adenocarcinoma (1 paper, 2025). "TXNIP expression is directly suppressed by androgens and diminishes during tumor initiation and progression, as demonstrated in both human samples and a prostate adenocarcinoma mouse model (TRAMP)." (PMID 41213907, 2025).
prostate tumor (1 paper, 2025). "Next, we investigated whether TXNIP recovery influence other key aspects of prostate tumor cell biology." (PMID 41213907, 2025).
psoriasis (1 paper, 2025). An autoimmune condition characterized by red, well-delineated plaques with silvery scales that are usually on the extensor surfaces and scalp. "Moreover, TXNIP, also known as Vitamin-D upregulated protein-1 (VDUP-1), interacts with thioredoxin to regulate redox responses, and has been identified as a factor determining the pathogenesis of skin diseases (e.g., psoriasis) during keratinocyte differentiation." (PMID 41440888, 2025).
retinal (1 paper, 2024). "To determine which glial cells may be the predominant site of TXNIP action in glaucomatous conditions, we examined the spatiotemporal consistency of glial activation and retinal inflammation levels in TXNIP-deficient and MCC950-treated COH mice." (PMID 39736512, 2024).
retinitis pigmentosa (1 paper, 2023). Retinitis pigmentosa (RP) is an inherited retinal dystrophy leading to progressive loss of the photoreceptors and retinal pigment epithelium and resulting in blindness usually after several decades. "The administration of AAV-Thioredoxin interacting protein (Txnip) treatment in mouse models of retinitis pigmentosa resulted in prolonged cone survival and improved vision." (PMID 38983010, 2023).
sterility (1 paper, 2021). "This suggests that critical MLX transcriptional targets in addition to TXNIP are responsible for the majority of the male-specific sterility phenotypes associated with loss of either MLX or MondoA." (PMID 34669700, 2021).
T-cell leukemia (1 paper, 2016). A malignant disease of the T-lymphocytes in the bone marrow, thymus, and/or blood. "For example, TXNIP can serve as an inhibitor for the activity of thioredoxin, a mediator of glucose metabolism, a tumor suppressor in T-cell leukemia or other cancers or a critical regulator of the differentiation of natural killer cells." (PMID 27224916, 2016).
testicular germ cell tumor (1 paper, 2022). A germ cell tumor arising from the testis. "We observed a statistical positive correlation of TXNIP expression and the estimated infiltration value of CAFs for the TCGA tumors of BRCA, BRCA-Basal, COAD, LIHC, LUSC, READ, STAD, and testicular germ cell tumors (TGCT) (all P < 0.05)." (PMID 35843949, 2022).
thyroid tumor (1 paper, 2014). A benign or malignant neoplasm affecting the thyroid gland. "Therefore, TXNIP expression appears to be downregulated or lost in the progression from well-differentiated thyroid tumors to more aggressive, undifferentiated tumors." (PMID 24645981, 2014).
urothelial carcinoma (1 paper, 2020). A malignant neoplasm derived from the transitional epithelium of the urinary tract (urinary bladder, ureter, urethra, or renal pelvis). "Interestingly, in urothelial carcinomas, the proportion of TXNIP-positive tumors correlates with tumor stage." (PMID 33081035, 2020).
uveitis (1 paper, 2022). An inflammatory process affecting a part of or the entire uvea. "Previously research reported that downstream HIF-1α signaling could facilitate Th17 differentiation; so we investigated whether melatonin alleviated uveitis via the oxidative stress/TXNIP/HIF-1α signaling axis." (PMID 35624485, 2022).
vascular dementia (1 paper, 2021). A degenerative vascular disorder affecting the brain. "Finally, targeting TXNIP seems to also be an interesting target in vascular dementia since acupuncture shows neuroprotective effects by decreasing TXNIP and NLRP3 expression-associated oxidative stress and inflammation in a rat model of the disease." (PMID 33567593, 2021).
vitiligo (1 paper, 2025). Generalized well circumscribed patches of leukoderma that are generally distributed over symmetric body locations and is due to autoimmune destruction of melanocytes. "Further quantitative measurement of phosphorylated ASK2/total ASK2 levels is required for the involvement of the ASK2/TXN/TXNIP pathway in decreased KC GPNMB expression and vitiligo pathogenesis." (PMID 39947468, 2025).
Von Hippel-Lindau syndrome (1 paper, 2024). "This interaction modulates the chromatin microenvironment by regulating H2AK119 ubiquitination and controlling the expression of FOXK2 target genes, including Von Hippel-Lindau syndrome (VHL), suppressor of cytokine signaling 1 and 2 (SOCS1/2), thioredoxin interacting protein (TXNIP), and others." (PMID 38741782, 2024).